ABL2 (ABL proto-oncogene 2, non-receptor tyrosine kinase)
Diseases named in the same sentence as ABL2 in open-access papers (continued):
Sharing a sentence is not in itself a finding about the gene and the disease.
hepatocellular carcinoma (3 papers, 2018 to 2023). A malignant tumor that arises from hepatocytes. "It was reported that high expression of ABL2 results in a poor prognosis in hepatocellular carcinomas, and the overexpression of ABL2 can promote cancer cell migration and invasion." (PMID 29875348, 2018).
pancreatic cancer (3 papers, 2018 to 2020). "This study also outlines additional mechanisms by which HCK, ABL2, and DDR1 may play a role in pancreatic cancer and fibrosis." (PMID 33213062, 2020). "This review outlines additional mechanisms by which HCK, ABL2, and DDR1 may play a role in pancreatic cancer and fibrosis." (PMID 33233470, 2020). "miR-193a accelerated pancreatic cancer cell cycle and stimulated cell proliferation and repopulation through inhibiting TGF-β2/TGF-βRIII/SMADs/E2F6/c-Myc signaling, and even destroyed normal intercellular junctions and promoted metastasis via repressing TGF-β2/TGF-βRIII/ARHGEF15/ABL2 pathway." (PMID 29433538, 2018).
bladder cancer (2 papers, 2022 to 2025). "ABL2 is up-regulated while miR-19b-1-5p is down-regulated in bladder cancer tissues and cell lines, according to another research." (PMID 36684446, 2022). "Recently, the research revealed that BMSCs-derived exosomal miR-19b-1-5p could inhibit bladder cancer cell lines (T24, UC3, 5637, and J82) from migrating, proliferating, or invading while promoting cell death via inhibiting ABL2, Bcl-2, MMP2 and MMP9." (PMID 36684446, 2022).
COVID-19 (2 papers, 2021 to 2023). A disease caused by infection with severe acute respiratory syndrome coronavirus 2. "In COVID-19, the inhibition of Abl2 by imatinib has been thought to block the Abl2 effects of VEGF on the pulmonary endothelium, a common ARDS scenario, as observed in COVID-19." (PMID 37108697, 2023).
glioma (2 papers, 2016 to 2023). A benign or malignant brain and spinal cord tumor that arises from glial cells (astrocytes, oligodendrocytes, ependymal cells). "In order to figure out the oncogene associated with glioma, we selected five genes to preform qRT-PCR experiments, including XPR1, QKI, CREB5, ACVR2B and ABL2." (PMID 37407973, 2023).
metastatic tumor (2 papers, 2018 to 2023). "In agreement with our above data, the mRNA levels of ABL2 and CTTN, but not of ABL1, were significantly higher in metastatic tumors compared with tumors that did not metastasize." (PMID 29774130, 2018).
non-small cell lung carcinoma (2 papers, 2016 to 2017). A group of at least three distinct histological types of lung cancer, including non-small cell squamous cell carcinoma, adenocarcinoma, and large cell carcinoma. "Depletion of ABL2 in non-small cell lung carcinoma cell lines led to decreased cell growth." (PMID 28086240, 2017).
virus infection (2 papers, 2022 to 2023). "Abl2 plays a role in reorganizing the cytoskeleton in response to viral infection, and its purpose is to increase the likelihood of intercellular merging to create syncytia through aiding the early stage of virus–cell membrane merging." (PMID 37376546, 2023). "As the Abl2 inhibitor imatinib was reported to impact MERS-CoV replication within 4 hpi, we postulated that CRK depletion might affect virus replication during the early stage of virus infection as well." (PMID 35060842, 2022).
alveolar rhabdomyosarcoma (1 paper, 2018). A rapidly growing malignant mesenchymal neoplasm. "Kinase targets found in the analysis were for osteosarcoma (KIT), Ewing’s sarcoma (ALK), undifferentiated pleomorphic sarcoma (JAK2, ABL2), alveolar rhabdomyosarcoma (NTRK1), and leiomyosarcoma (ALK)." (PMID 29541442, 2018).
Anxiety (1 paper, 2021). Intense feelings of nervousness, tension, or panic often arise in response to interpersonal stresses. "A role for Abl2, Csmd2, Dlgap1, and Isl1 in neurodevelopment and psychiatric and neurodegenerative diseases have been reported in previous studies and our association analysis suggests a role in anxiety." (PMID 33431988, 2021).
asthma (1 paper, 2022). "Using bioinformatics analysis, the target genes interacting with miRNAs related to the airway inflammatory response, airway remodeling and other pathological change processes in asthma were screened as ABL2, MMP16 and PDE7A." (PMID 36611831, 2022).
B-cell lymphomas (1 paper, 2023). "A gene expression study carried out on transformed B-cell lymphomas indicated an increase in ABL2 gene expression upon transformation of follicular lymphoma to DLBCL." (PMID 36831263, 2023).
gastric adenocarcinoma (1 paper, 2007). "ABL2 (up) tyrosine kinase is related to proto-oncogene ABL, and is implicated in hematologic neoplasms and gastric adenocarcinoma." (PMID 19455236, 2007).
lymph node metastasis (1 paper, 2024). "We observed significant differences in the expression of ABL2 in different patients with GC, which may be attributed to cancer types, H.pylori infection, and lymph node metastasis." (PMID 39308677, 2024).
lymphoma (1 paper, 2023). A malignant (clonal) proliferation of B- lymphocytes or T- lymphocytes which involves the lymph nodes, bone marrow and/or extranodal sites. "We proposed the idea that such a change in expression may result as a consequence of genetic alterations such as inversions, and inversion of ABL2 may act as a biomarker to distinguish DLBCL from other lymphomas." (PMID 36831263, 2023).
medulloblastoma (1 paper, 2025). A malignant, invasive embryonal neoplasm arising from the cerebellum. "ABL2 amplification has been reported in primary solid and hematologic tumors and in medulloblastoma, the expression of ABL1 and ABL2 has been associated with shorter survival rates." (PMID 40332023, 2025).
neuroblastoma (1 paper, 2026). Neuroblastoma (NB) is the most common solid, extracranial childhood tumor. "Overall, we concluded that the DANCR/miR-125a-5p/ABL2/SSH1/cofilin signaling pathway regulated the metastatic ability of neuroblastoma." (PMID 41602364, 2026). "In our studies, we found that DANCR promoted the metastatic ability of neuroblastoma cells by targeting its downstream gene ABL2." (PMID 41602364, 2026). "In summary, our findings delineate the DANCR/miR-125a-5p/ABL2/cofilin axis as a critical regulator of cytoskeletal dynamics in neuroblastoma metastasis, offering novel insights for the diagnosis and therapeutic targeting of high-risk neuroblastoma." (PMID 41602364, 2026). "Our study highlights the role of DANCR in neuroblastoma metastasis, emphasizes its regulatory relationship with miR-125a-5p and ABL2, and provides a new perspective for neuroblastoma therapy." (PMID 41602364, 2026). "As the first encouraging result, we verified that DANCR promoted neuroblastoma cell proliferation and metastasis via the upregulation of ABL2." (PMID 41602364, 2026). "Together, we concluded that DANCR promoted ABL2-mediated proliferation and metastasis by acting as a ceRNA by decoying miR-125a-5p in neuroblastoma." (PMID 41602364, 2026). "We verified that DANCR overexpression in neuroblastoma cells significantly enhances the interaction of ABL2 with cortactin, which also affects SSH1-cofilin activity and stabilizes F-actin networks." (PMID 41602364, 2026). "In conclusion, the results of the present study revealed that DANCR functions as a ceRNA to aggravate neuroblastoma metastasis by targeting the miR-125a-5p/ABL2/cofilin axis." (PMID 41602364, 2026). "Crucially, our study links DANCR to ABL2-driven cytoskeletal dynamics in neuroblastoma." (PMID 41602364, 2026). "Here, we examined the influence of ABL2 on neuroblastoma metastasis." (PMID 41602364, 2026). "Therefore, our study suggests that DANCR is an oncogenic lncRNA that promotes neuroblastoma progression via the DANCR/miR-125a-5p/ABL2 axis, which may serve as a novel prognostic biomarker and therapeutic target for neuroblastoma." (PMID 41602364, 2026). "The total RNA of 64 neuroblastoma tissue samples was extracted for further validation of the relationships among miR-125a-5p, DANCR, and ABL2." (PMID 41602364, 2026). "Moreover, we revealed a negative correlation between DANCR/ABL2 and miR-125a-5p in neuroblastoma samples by Pearson correlation analysis." (PMID 41602364, 2026).
prion disease (1 paper, 2022). A transmissible disease that is caused by a protein that is able to induce abnormal folding of normal cellular proteins, leading to characteristic spongiform brain changes, which are associated with neuronal loss without an inflammatory response.
prostate tumors (1 paper, 2013). "In prostate tumors, c-Abl and/or Abl2 expression was significantly increased as assessed by immunohistochemistry [IHC])." (PMID 24223753, 2013).
sarcoma (1 paper, 2018). A usually aggressive malignant neoplasm of the soft tissue or bone. "A mutation of ABL2 was demonstrated in a patient with undifferentiated pleomorphic sarcoma." (PMID 29541442, 2018).
triple-negative breast carcinoma (1 paper, 2021). An invasive breast carcinoma which is negative for expression of estrogen receptor (ER), progesterone receptor (PR), and human epidermal growth factor receptor 2 (HER2). "Using an intracardiac mouse model of metastasis, shRNA-mediated knockdown of both ABL1 and ABL2 in bone tropic triple-negative breast cancer cells decreased metastasis to the bone and increased overall survival." (PMID 34022881, 2021). "In the triple-negative breast cancer MDA-MB-231 cell line, stimulation of the epidermal growth factor receptor (EGFR) increased ABL2 activity and promoted cortactin-mediated invadopodia formation." (PMID 34022881, 2021).
Williams-Beuren syndrome (1 paper, 2015). "Such functions are also known for the genes that are ECpiC loci, such as the oncogenic transcription factors ABL2 and ELK4, the miRNA effector AGO2, and TBL2 and KCTD7 genes that are in the deleted locus of Williams-Beuren syndrome patients, which display developmental defects." (PMID 26588211, 2015).
cancer (40 papers, 2010 to 2026). A tumor composed of atypical neoplastic, often pleomorphic cells that invade other tissues. "The relatively high mutation frequency of BRCA in CNV analysis across 31 types of cancers, especially in genes such as ABL2 and BTG2, further underlines the extreme complexity of BRCA patient heterogeneity." (PMID 40332226, 2025). "On the other hand, miR-193a destroyed normal intercellular junctions through repressing TGF-β2/TGF-βRIII/ARHGEF15/ABL2 signaling, and caused the repopulated cancer cells to deviate from the primary sites and migrate for metastasis." (PMID 29433538, 2018). "Genes with putative miR-200a targeting sequences that have been implicated in cell migration and cancer include Abelson murine leukemia viral oncogene homolog 2 (Abl2), deleted in liver cancer 1 (Dlc1), Eph receptor A7 (EphA7), and Zeb1." (PMID 20957176, 2010). "For instance, nine of our candidate cancer genes were also contained in the Cancer Gene Census list, which comprises 487 genes causally linked to cancer, representing a highly significant enrichment (Abl2, Braf, Fbxw7, Foxp1, Ipo11, Mllt3, Fas, Pten, and Nf1; p<0.0002, Fisher’s exact test)." (PMID 23940809, 2013). "ABL2 has also been broadly reported as a proliferation- and metastasis-related gene in various cancers." (PMID 41602364, 2026). "ABL2 involved in the development of various cancer types by regulating cytoplasmic signaling pathways that influence cell survival, proliferation, and migration." (PMID 41415030, 2025). "These suggested that ABL2 usually acts as a cancer-promoting gene in cancers, including GC, CC and RCC." (PMID 39308677, 2024). "Therefore, it is crucial to continue collecting and analyzing samples from patients with GC to comprehensively understand ABL2's relation to cancer types or other parameters." (PMID 39308677, 2024). "The ABL2 gene encodes a nonreceptor tyrosine kinase, and its role in cancer has been studied, particularly in the context of cell signaling, cell migration, and invasion." (PMID 37958341, 2023). "ABL2 inhibition decreases CXCL12/CXCR4-induced cancer cell invasion." (PMID 33233470, 2020). "Of note, the 5 shared candidate cancer genes of tumors 05 and 09 (Pten, Fas, Esr1, Abl2, Lrp1b) were independently obtained in both tumors with similar average read frequencies, confirming the robustness of our sequencing method to identify clonal expansion of insertions." (PMID 23940809, 2013). "However, the role of ABL2 may be context dependent with ABL2 demonstrating tumor suppressive properties in some cancer models." (PMID 33233470, 2020). "We discovered and validated that concurrent targeting of FYN, along with other tyrosine kinases such as IGF1R, EGFR, or ABL2 can synergistically eradicate TNBC and impede cancer growth." (PMID 40243589, 2025). "Inhibiting ABL2 blocks the activity of HSF1 and its targets, which are essential for cancer cell growth and survival." (PMID 37958341, 2023). "Further, via the ABL2 protein intermediate, AXL can also act upstream of TAZ in some cancer types to promote a feed-forward activation loop amenable to therapeutic intervention." (PMID 33408328, 2021). "Subpopulation B consisted of 121 cells (29.1%) and showed overexpression of 13 genes, including seven cancer genes (HSPB1, ANXA1, SLPI, KRT8, KRT19, KLK7, and ABL2) and several Keratin genes (KRT8, KRT7, KRT19, and KRT6B)." (PMID 28794488, 2017). "ABL1 and ABL2 display mutations in approximately 1.5% and 4% of NSCLC cases, respectively, and ABL2 is amplified in approximately 8% of NSCLC cases (adapted from cBio Cancer Genomics Portal)." (PMID 26758680, 2016).
cancer (continued). "In addition to influencing T cell differentiation, ABL2 and PAG1 have been identified as potential therapeutic targets in cancer." (PMID 40282426, 2025). "We determined that EPHB2 has significant interactions with several key proteins, including L1CAM, ABL2, KDM4A, BTF3, and SRC, suggesting that it may form a functional network critical to cancer progression." (PMID 41322437, 2025). "Immunohistochemistry detected ABL2 expression in 57 GC patients, and found that ABL2 expression increased within cancer samples relative to corresponding non-tumor tissues." (PMID 36104322, 2022). "To evaluate if IST5 affects kinase activity in cancer cells, we tested kinase inhibitory activity of IST5 in two custom-tailored panels including 54 relevant kinases, including Jak1, Jak2, Jak3, Tyk2, Abl1, Abl2, Lck, Fyn, Src and TrkB/C." (PMID 33217941, 2020). "Collectively, these findings indicate that the inhibitory effect of IST5 on Stat5 phosphorylation in cancer cells is not due to inhibition of Jak2 or other key kinases including Jak1, Jak3, Tyk2, Src, Lck, Fyn, TrkB/C, Abl1 or Abl2." (PMID 33217941, 2020). "To investigate whether the HMA-resistance-specific CNAs influence gene expression, we assayed the expression of 8 cancer-related genes by quantitative reverse transcription PCR (RT-qPCR) including BCL9, ARNT, ABL2, STK11, TCF3, SMARCA4, RUNX1, and U2AF1." (PMID 28052028, 2017). "Consequently, it would be more reasonable to consider ABL2 for a panel of genes indicating cancer invasiveness rather than using it as an individual biomarker to characterize cell invasiveness in a randomly chosen lung tumor." (PMID 39329988, 2024).
tumor (29 papers, 2013 to 2026). "Prolonged activation of ABL2 disrupted Rac1-mediated assembly of β1-integrin causing perturbed laminin assembly and inverted epithelial cell polarity reminiscent of the early cellular changes following tumor initiation." (PMID 34022881, 2021). "It is noteworthy that PDRWH also identified known tumor-specific drivers that were missed by other methods, such as ABL2 for BRCA, SETBP1 for KIRC, NIN and TOP2A for STAD." (PMID 38683860, 2024). "At the same time, uncontrolled expression of ABL2 promoted the invasion and maturation of invadopodia in tumor cells." (PMID 39329988, 2024). "ABL2 plays a critical role in influencing the invasiveness of tumor cells by reorganizing their cytoskeleton." (PMID 39329988, 2024). "Tumor growth curves with silenced circPGD and ABL2 significantly decreased compared with control of MGC-803 cells." (PMID 36104322, 2022). "The consequences of elevated expression of ABL1 and ABL2 for tumor progression are cell context-dependent." (PMID 34022881, 2021). "GISTIC analysis for amplifications and deletions depicted copy number gain and amplification in ABL2 and CTTN, where the majority of tumor samples had gain or amplification in ABL2." (PMID 29774130, 2018). "Notably, ABL2 promotes tumor cell invasion and dissemination while simultaneously suppressing local tumor growth." (PMID 41602364, 2026). "To date, numerous studies have explored the role of ABL2 in the invasiveness of tumor cells." (PMID 39329988, 2024). "The ABL kinases, ABL1 and ABL2, promote tumor progression and metastasis in various solid tumors." (PMID 34022881, 2021). "In addition to tumor cell behaviors such as cell invasiveness, integrin-ABL2 signaling also regulates fibroblast cell behaviors such as proliferation, adhesion-dependent cell edge protrusion, and perhaps even activation." (PMID 33233470, 2020). "In addition, some mutations that were found in other types of tumor like CDK6, PIK3C2B, and ABL2 also occurred in our PDCs." (PMID 28029662, 2017). "Interestingly, we observed EGF-induced alternative promoter usage of genes that have previously been implicated in tumor progression (e.g., VEGFC, PTK2, IL18 and VAV3) or in cell survival/proliferation (e.g., FBXW7, BID, ABL2)." (PMID 24324612, 2013). "Furthermore, overexpression of miR-143-3p may also enhance anti-tumor effects by targeting ABL2 and PAG1." (PMID 40282426, 2025). "However, despite these difficulties, ponatinib induced tumor regression in all treated mice, indicating that the mechanism of D/T + nilotinib resistance may involve ABL1 or ABL2 mutation." (PMID 33122628, 2020). "Following treatment with nilotinib or genetic inhibition of ABL1/ABL2, cancer cells were sensitized to BRAF and MEK inhibitors and underwent cell death as well as decreased tumor growth." (PMID 34022881, 2021). "Additionally, two cases (RB36 and RB37) showed CNA in ABL2 and MDM4 genes, with the latter alteration found only in the tumor sample." (PMID 40332023, 2025). "CNAs in ABL2, MDM3, and MYCN genes were identified in 18 tumor samples." (PMID 40332023, 2025). "The chances of finding an occasional ABL2 mutation in a solid tumor and an NSCLC tumor are higher, while they also do not exceed 20–35%." (PMID 39329988, 2024). "Likewise, analysing all predicted miRNA-oncogene interactions among the 231 COSMIC oncogenes, there were only 2 showing significant anticorrelation across tumour types with their predicted target miRNA (ESR1 and ABL2)." (PMID 30531873, 2018).
tumor (continued). "Further, we detected relatively lower expression of TGF-β2, TGF-βRIII, ARHGEF15 and ABL2 in both SW1990- and PANC-1-reporter cells co-cultured with irradiated feeder cells than those with untreated ones in vitro, and similarly in irradiated tumor tissues than in the untreated ones in vivo." (PMID 29433538, 2018).